GSK3B (glycogen synthase kinase 3 beta)
Diseases named in the same sentence as GSK3B in open-access papers (continued):
Sharing a sentence is not in itself a finding about the gene and the disease.
myocarditis (3 papers, 2019 to 2023). Myocarditis is a condition that is characterized by inflammation of the heart muscle (myocardium). "By combining PD-L1-related proteins, we found that mTOR, GSK3β, PTPN11, and MFN2 may be potential diagnosis and treatment biomarkers of ICI-associated myocarditis." (PMID 36760573, 2023). "By analyzing coexpressed proteins, we found four hub proteins that may lead to the occurrence of ICI-related myocarditis, mammalian target of rapamycin (mTOR), GSK3β, PTPN11, and MFN2." (PMID 36760573, 2023). "Second, we confirmed that mTOR, GSK3β, PTPN11 and MFN2 are highly expressed in ICI-related myocarditis by proteomic sequencing, cellular experiments are required to verify our hypothesis." (PMID 36760573, 2023).
non-alcoholic fatty liver disease (3 papers, 2014 to 2025). "NDUFA8 (Cluster 5), NDUFS6, and GSK3B (Cluster 2) were mapped to “Non-alcoholic fatty liver disease (NAFLD)”." (PMID 28445522, 2017). "In the progression of non-alcoholic fatty liver disease (NAFLD), overactivation of GSK-3β is a critical molecular node linking lipid metabolic disorders, insulin resistance, hepatic inflammation, and fibrosis." (PMID 41393953, 2025).
peritonitis (3 papers, 2014 to 2024). Inflammation of the peritoneum (tissue that lines the abdominal wall and covers most of the organs in the abdomen). "Moreover, in mice with hematopoietic cell-specific GSK3β deficiency and heterozygous GSK3β+/− mice, signs of inflammation were significantly reduced in a peritonitis model." (PMID 39125833, 2024). "In murine Pam3CSK4-induced peritonitis, the number of inflammatory cells in the peritoneum was significantly reduced in GSK3β+/− mice or in the absence of one or both GSK3β alleles in bone marrow cells." (PMID 39125833, 2024). "For another substance leading to GSK3β-inhibition, i.e., ephedrine hydrochloride, anti-inflammatory effects have been shown in the murine peptidoglycan-induced peritonitis model, as reflected by increased IL-10 and decreased TNF, IL-1β, and IL-6 secretion by peritoneal macrophages." (PMID 39125833, 2024). "Moreover, in heterozygous GSK3β+/- mice exhibiting Pam3CSK4-induced peritonitis, the extent of inflammation was significantly lower than in the wildtype and equivalent results have been obtained in chimeric mice possessing GSK3β KO hematopoietic cells." (PMID 32231133, 2020). "In mice with peptidoglycan (PGN)-induced peritonitis, anti-inflammatory effects (increased IL-10, decreased TNF, IL-1β, IL-6) could be elicited by ephedrine hydrochloride (EH), a substance that inhibits GSK3β via the PI3K-Akt axis in cell culture experiments (see Section 3.1.3)." (PMID 32231133, 2020).
polycystic kidney disease (3 papers, 2015 to 2023). A usually autosomal dominant and less frequently autosomal recessive genetic disorder characterized by the presence of numerous cysts in the kidneys leading to end-stage renal failure. "NEK1 and CTNNB1, together with AXIN1, GSK3B and TSC2, participate in the Wnt signaling pathway in urological cancer cells and polycystic kidney disease (PKD)." (PMID 26317783, 2015).
urothelial carcinoma (3 papers, 2011 to 2024). A malignant neoplasm derived from the transitional epithelium of the urinary tract (urinary bladder, ureter, urethra, or renal pelvis). "PI3-kinase and AKT cause an upregulation of p21 by suppressing GSK-3β activity and activating mTOR in both cultured human urothelial carcinoma cells and mouse urothelial cells in vivo." (PMID 21864408, 2011). "Consistent with a role for FEME in EGFR signaling, the stable silencing of Endophilin increases phosphorylation of AKT, GSK3β, SFK and STAT3 after EGF stimulation, mimicking the signaling pattern in urothelial carcinoma." (PMID 32589750, 2020).
acute lymphoblastic leukemia (2 papers, 2017 to 2026). Leukemia with an acute onset, characterized by the presence of lymphoblasts in the bone marrow and the peripheral blood. "This is unlike what has been described in acute lymphoblastic leukemia (ALL) where GSK-3β suppression sensitizes ALL cells to NF-κB-mediated apoptosis via survivin effect." (PMID 29383130, 2017).
acute pneumonia (2 papers, 2024 to 2025). "Comparably, GSK3β activity was enhanced in alveolar macrophages of rats suffering from pneumocystis carinii-induced pneumonia, while healthy animals had markedly higher p-GSK3β-Ser9 levels." (PMID 39125833, 2024). "Therefore, we hypothesized that KP might alleviate the P. aeruginosa-induced acute pneumonia by regulating the GSK3β/JNK/c-Jun and NF-κB signaling pathways." (PMID 40143103, 2025).
acute promyelocytic leukemia (2 papers, 2015 to 2023). An aggressive form of acute myeloid leukemia (AML), characterized by arrest of leukocyte differentiation at the promyelocyte stage, due to a specific chromosomal translocation t(15;17) in myeloid cells. "We found that propofol initiates PI3-kinase/AKT-mediated GSK-3β inactivation and Mcl-1 stabilization, rescuing the constitutive apoptosis in primary neutrophils and granulocyte-differentiated acute promyelocytic leukemia HL60 cells." (PMID 26061531, 2015).
adrenoleukodystrophy (2 papers, 2018 to 2022). A peroxisomal disorder resulting in cerebral demyelination, axonal dysfunction in the spinal cord leading to spastic paraplegia, adrenal insufficiency and in some cases testicular insufficiency. "Aberrant activity of GSK3β has also been linked to peroxisomal disorders; GSK3β activity was increased in the nervous system of mouse models for adrenoleukodystrophy and rhizomelic chondrodysplasia punctata and in patient fibroblasts." (PMID 35019937, 2022).
AIDS dementia (2 papers, 2020 to 2022). "Expression levels of the molecules of interest, GSK-3β, β-catenin, NF-κB, and IL-6 from the Red/Green-HIV-1 infected human astrocyte data were overlaid with HIV encephalitis (HIVE) and HIV-associated dementia (HAD) disease and biological function using IPA pathway explorer." (PMID 33171974, 2020).
alcoholic liver diseases (2 papers, 2018 to 2023). A disorder caused by damage to the liver parenchyma due to alcohol consumption. "According to our data, miR-183-5p targets FOXO1, SMAD4, and GSK3B genes involved in transcriptional misregulation in cancer, FOXO signaling pathway and alcoholic liver disease." (PMID 37168369, 2023).
androgenetic alopecia (2 papers, 2016 to 2024). "When androgen treated DPC in androgenic alopecia patients, β-catenin was significantly decreased in the cytoplasm, while GSK-3β was increased." (PMID 27974900, 2016).
ankylosing spondylitis (2 papers, 2019 to 2024). An autoimmune chronic inflammatory disorder characterized by inflammation in the vertebral joints of the spine and sacroiliac joints. "MiR-124 regulates osteoblast differentiation through GSK-3β in ankylosing spondylitis." (PMID 31480018, 2019).
aortic aneurysm (2 papers, 2022 to 2023). A ruptured aneurysm located in the wall of the proximal portion of the descending aorta proceeding from the arch of the aorta. "The role of GSK3β in the development of aortic aneurysms is not entirely clear." (PMID 36669494, 2023).
B-cell lymphomas (2 papers, 2017 to 2022). "The effects of GSK-3β across various histologic subtypes of aggressive B-cell lymphomas and according to c-MYC status have yet to be explored." (PMID 29383130, 2017). "By contrast, little is known about the significance of GSK-3β in B-cell lymphoma pathogenesis, resistance to therapy, and survival despite its known function as a metabolic checkpoint regulator in B-cells." (PMID 29383130, 2017). "Our results show that GSK-3β targeting leads to decreased proliferation and viability of all aggressive B-cell lymphoma cell lines tested by inducing variable effects on pro-survival signals and DNA damage response, ultimately leading to apoptosis." (PMID 29383130, 2017). "However, in B-cell NHLs, GSK-3β activity could be also downmodulated via proteasomal degradation of GSK-3β itself, due to interactions with Inhibitor of Bruton’s tyrosine kinase α (IBTKα)." (PMID 35681507, 2022).
Barrett esophagus (2 papers, 2019 to 2022). Esophageal lesion lined with columnar metaplastic epithelium which is flat or villiform. "APEX1 redox function was required for GSK-3β-mediated APEX1 regulation of Nrf2 in Barrett’s related esophageal adenocarcinoma cells." (PMID 35311089, 2022). "Acid-dependent and inflammation-induced damage leads to progression of Barrett’s esophagus, which could potentially contribute to TNF-α-promoted tumor growth and metastasis via PI3K/Akt, GSK3β, and NF-κB." (PMID 30841855, 2019).
brain inflammation (2 papers, 2011 to 2024). "Bacterial-derived brain inflammation may exacerbate Tau pathology through up-regulating GSK-3β activity, while PP2A inhibition decreases GSK-3β activity, promoting phosphorylation at the Ser9 site." (PMID 38362505, 2024). "On the other hand, GSK-3β also functions as a negative regulator of pro-inflammatory cytokine expression and decreased GSK-3β expression may render Pink1−/− mice more vulnerable to TNF-α, IL-1β and LPS-induced brain inflammation." (PMID 21249202, 2011).
cholestasis (2 papers, 2024 to 2025). Impairment of the bile flow caused by obstruction within the liver, or outside the liver in the bile duct system. "SAL increased p-GSK-3β expression and inhibited cholestasis-induced GSK-3β activation, inhibiting HSC activation." (PMID 38808258, 2024). "In the GFPG-H group, PI3K, p-AKT/AKT, and Bcl-2 levels were significantly higher (P < 0.05, P < 0.01, P < 0.001), while GSK-3β, caspase-3, and Bax expression was significantly lower (P < 0.05, P < 0.001) compared to the ANIT-induced cholestasis group." (PMID 40956833, 2025). "Compared to the normal group, the cholestasis model group showed significantly reduced PI3K, p-AKT/AKT, and Bcl-2 expression (P < 0.05, P < 0.01), while GSK-3β, caspase-3, and Bax levels were significantly increased (P < 0.05, P < 0.01, P < 0.001)." (PMID 40956833, 2025).
chronic asthma (2 papers, 2013 to 2016). An asthma that is characterized by the development of persistent airway inflammation and recurrent attacks of breathlessness and wheezing, which vary in severity and frequency. "In mice sensitized with ovalbumin, AKR1B1 inhibition with fidarestat prevented the airway remodeling observed in chronic asthma by blocking the tumor growth factor β (TGFβ), phosphatidylinositol-4,5-bisphosphate 3-kinase (PI3K)/Protein kinase B (PKB/AKT)/Glycogen synthase kinase-3 beta (GSK3B) axis." (PMID 27540362, 2016). "Thus, in summary, our results from the present studies demonstrate that AR mediates airway remodeling via PI3K/AKT/GSK3β-PAK pathway and that its inhibition blocks the progression of remodeling in the experimental models of chronic asthma." (PMID 23460857, 2013).
cleft palate (2 papers, 2012 to 2019). Cleft palate is a fissure type embryopathy that affects the soft and hard palate to varying degrees. "Moreover, homozygous knockout of Gsk3b, which encodes a β-catenin-degrading enzyme in the canonical Wnt signaling pathway, results in mice displaying full cleft palate, suggesting that excessive β-catenin signaling also causes cleft palate in these mouse models." (PMID 30760477, 2019). "We have shown previously that all GSK-3β knockouts die at birth with cleft palates and skeletal defects." (PMID 23185619, 2012).
colon adenocarcinoma (2 papers, 2013 to 2023). "The expression of upstream survival signals (GSK-3β, β-catenin, c-myc and cyclin D1) in human colon adenocarcinoma Caco-2 cells was evaluated after epirubicin treatment with or without galectin-3 knockdown." (PMID 24303084, 2013). "In this study, we examined the effects and mechanisms of silencing galectin-3 via RNA interference (RNAi) on the β-catenin/GSK-3β pathway in human colon adenocarcinoma Caco-2 cells." (PMID 24303084, 2013).
demyelinating disease (2 papers, 2022 to 2026). A broad group of disorders that affect the myelin sheaths that cover the neurons. "This review examines pharmacological targeting of PI3K/Akt/mTOR and Wnt/GSK-3β signaling and describes intracellular mechanisms involved in oligodendrocyte and neuronal differentiation, with consideration of therapeutic application in demyelinating diseases." (PMID 42274605, 2026). "In this sense, inhibitors of glycogen synthase kinase 3β (GSK3β) and phosphodiesterase 7 (PDE7) have recently shown great therapeutic potential for the treatment of demyelinating diseases." (PMID 36430856, 2022).
disc degeneration (2 papers, 2021 to 2024). "In an IDD mouse model, GSK3β was downregulated in intervertebral disc tissues, and upregulating GSK3β mitigated NP cell apoptosis and disc degeneration in IDD mice by repressing HDAC4." (PMID 38217540, 2024). "In IDD mice, GSK3β overexpression resulted in increased DHI, inhibition of NP cell apoptosis, alleviation of disc degeneration, and promoted mechanical and thermal pain thresholds." (PMID 33691773, 2021).
dysplasia (2 papers, 2016 to 2021). A usually neoplastic transformation of the cell, associated with altered architectural tissue patterns. "Our findings show that moderate and poorly differentiated OSCC samples depict increased nuclear localization of GSK-3β, compared to oral dysplasia samples, which show mostly a cytoplasmic localization." (PMID 34564680, 2021). "Furthermore, we found a progressive shift of p-GSK-3βSer9 to the nucleus associated with increase in p-β-cateninSer552 during progression from hyperplasia through dysplasia to carcinoma confirming the inactivation of GSK-3β." (PMID 26902162, 2016).
endometrial tumors (2 papers, 2012 to 2018). "If GSK3β were indeed critical for EC tumour maintenance, then it would be plausible to hypothesise that AKT-GSK3β axis would be impaired in endometrial tumours, to maintain high levels of GSK3β activity." (PMID 29724995, 2018).
Familial adenomatous polyposis (2 papers, 2010 to 2017). Familial adenomatous polyposis (FAP) is characterized by the development of hundreds to thousands of adenomas in the rectum and colon during the second decade of life. "In mouse model of familial adenomatous polyposis (FAP), thymoquinone interfered with polyp progression by inducting tumor-cell specific apoptosis and by modulating Wnt signaling through the activation of GSK-3β, thus reducing the risk of colorectal cancer." (PMID 28881699, 2017).
Fanconi anemia (2 papers, 2021 to 2025). Fanconi anemia (FA) is a hereditary DNA repair disorder characterized by progressive pancytopenia with bone marrow failure, variable congenital malformations and predisposition to develop hematological or solid tumors.
fragile X syndrome (2 papers, 2017 to 2025). A genetic syndrome caused by mutations in the FMR1 gene which is responsible for the expression of the fragile X mental retardation 1 protein. "Resultant hyper-activation of GSK3β has been shown in animal models of Fragile X Syndrome (FXS), a syndromic form of ASD." (PMID 35445171, 2017).
gestational diabetes (2 papers, 2014 to 2023). Carbohydrate intolerance first diagnosed during pregnancy. "GSK3β is implicated in inflammatory processes, increasing IL-1β and MCP-1, among other pro-inflammatory cytokines, in the adipose tissue of women with gestational diabetes." (PMID 37108229, 2023).
Gliosis (2 papers, 2021 to 2026). Gliosis is the focal proliferation of glial cells in the central nervous system. "PS128 supplementation prevented the damage induced by icv-STZ by reducing the levels of fecal PPA, GSK3β activity, and gliosis in 3 × Tg-AD mice." (PMID 34627204, 2021). "PS128 supplementation prevents damage induced by intracerebroventricular injection of streptozotocin by regulating the propionic acid levels, glycogen synthase kinase 3 beta activity, and gliosis in 3 × Tg-AD mice." (PMID 34627204, 2021). "PS128 supplementation effectively prevented the damage induced by icv-STZ by reducing the fecal PPA levels, GSK3β activity, and gliosis in 3 × Tg-AD mice." (PMID 34627204, 2021). "In vivo studies in mice demonstrated increased GSK‐3β phosphorylation, which inhibited its activity in the hippocampus without altering plasma lithium levels or causing gliosis." (PMID 41020548, 2026). "According to our findings, the administration of icv-STZ exacerbated the disease progression of AD via gliosis that resulted from an increases in the levels of fecal PPA and the inactive form of GSK3β in 3 × Tg-AD mice." (PMID 34627204, 2021). "Gliosis resulting from PPA and GSK3β was considered one of the possible mechanisms that attenuated disease progression in the AD mouse model." (PMID 34627204, 2021).
hepatitis B (2 papers, 2021 to 2023). "In the study of hepatitis B virus (HBV) infection, Sirt2 overexpression was associated with Akt activation, which consequently downregulated glycogen synthase kinase 3β (GSK-3β) and increased β-catenin levels." (PMID 34925016, 2021).
HIV-1 infection (2 papers, 2011 to 2016). The type species of lentivirus and the etiologic agent of acquired immunodeficiency syndrome (AIDS). "Of note, inhibition of GSK3β upon HIV-1 infection resulted in nuclear NFAT localization in approximately 90% of cells, irrespective of functional Vpr expression." (PMID 27383627, 2016).
Hydrocephalus (2 papers, 2019). Hydrocephalus is an active distension of the ventricular system of the brain resulting from inadequate passage of CSF from its point of production within the cerebral ventricles to its point of absorption into the systemic circulation. "While none of the Igf1(+/tg) or Igf1(tg/tg) transgenic mice developed craniosynostosis, 23% of the Gsk3β(+/-) mice displayed craniosynostosis and/or presumed hydrocephalus, a previously undescribed phenotype with incomplete penetrance." (PMID 31442251, 2019). "Fifteen percent of Gsk3β(+/-) mice had suture fusion, one of which had increased biparietal diameter suggestive of hydrocephalus." (PMID 31442251, 2019).
intervertebral disc degeneration (2 papers, 2021 to 2024). "At the molecular level, the literature suggests that intervertebral disc degeneration and tau protein hyperphosphorylation are both regulated through the AMPK/GSK3β pathway." (PMID 38461266, 2024).
keratitis (2 papers, 2013 to 2021). A corneal disease that is characterized by inflammation of the cornea. "However, in PA keratitis, specific GSK3β inhibitor SB216763 and LiCl displayed different effects in inflammatory cytokine expression, which indicated the participation of other signaling pathways in the LiCl-induced anti-inflammatory responses." (PMID 23878501, 2013).
kidney injury (2 papers, 2020 to 2022). Trauma to the kidney. "GSK3β-Nrf2-HO-1 mediated oxidative signaling and the microglial/macrophage polarization-related inflammatory pathway are likely involved in adenine-induced kidney injury and memory deficits, and are reversed by fucoidan treatment." (PMID 35447931, 2022).
kidney tumor (2 papers, 2009 to 2018). "It is interesting to note that oncocytomas, which are benign kidney tumours, showed only cytoplasmic expression of GSK-3β and no pGS was detected in these tumours." (PMID 19920820, 2009).
Knee Osteoarthritis (2 papers, 2015 to 2020). "We indeed found the extent of GSK3β inactivation in OA cartilage correlated with BMI, recently recognized together with age as one of the potential predictor factors for knee osteoarthritis." (PMID 26618897, 2015).
left ventricular hypertrophy (2 papers, 2013 to 2022). Enlargement of the LEFT VENTRICLE of the heart. "In addition, downregulation of the PI3Kα/Akt/GSK3β and nuclear factor kappa-B (NF-κB) signaling pathways may reverse left ventricular hypertrophy and improve myocardial status." (PMID 35915792, 2022).